PARG (poly(ADP-ribose) glycohydrolase)
Diseases named in the same sentence as PARG in open-access papers (continued):
Sharing a sentence is not in itself a finding about the gene and the disease.
tumor (continued). "Our use of a novel class of PARG inhibitor to selectively kill tumour cells with particular genetic defects, combined with our data generated using Gallotannin and PARG siRNA support the future development of PARG inhibitors as mono-therapeutic agents." (PMID 28254358, 2017). "Taken together, these results provided strong evidences to show that PARG silencing suppressed tumor development from BaP-induced transformed cells in vivo." (PMID 27003318, 2016). "We found that the tumors formed by shPARG cells showed a dramatically lower level of PARG protein expression than the tumor formed by 16HBE cells." (PMID 27003318, 2016). "The aim of this study is to investigate the effect of PARG deficiency on BRCA1- and/or PTEN-deficient tumour cells." (PMID 27375368, 2016). "This supports the application of a PARG inhibitor to exploit synthetic lethal-mediated killing of pathway defective tumour cells." (PMID 23251397, 2012). "PARG staining of tumours was classified as null, slight (1+), medium (2+) or strong (3+)." (PMID 41451844, 2025). "As a result, we cannot determine whether PARG expression remained stable or changed during tumour progression." (PMID 41451844, 2025). "Therefore, two key factors involved in the effectiveness of PARP/PARG inhibition in tumour cell radiosensitisation appear to be HR proficiency, but also the LET (and CDD-dependence) of the radiation." (PMID 38368415, 2024). "Hence, the increased dependence of PARG;BRCA2-deficient cells on EXO1/FEN1 function is also relevant in human tumor cells." (PMID 38360994, 2024). "We also demonstrate that OGG1 and PARG inhibitors can exacerbate the impact of high-LET protons in tumour cell killing, and therefore could represent a novel therapeutic strategy, such as in the treatment of HNSCC." (PMID 38368415, 2024). "In vitro and in vivo experiments showed that silencing PARG inhibited PDAC tumor growth." (PMID 36053937, 2023). "Furthermore, poly (ADP-ribose) glycohydrolase (PARG), an enzyme that degrades pADPr, has been reported to be downregulated in tumor tissues with abnormally high levels of pADPr." (PMID 35585513, 2022). "Genes involved in angiogenesis pathway were down-regulated upon PARG overexpression that could decrease blood supply induction and inhibit tumor growth." (PMID 34638458, 2021). "Given that the reduction of PARG activity can significant elevate the PARylation cellular level, implying that PARG inhibitors may block the HNRNPH1 related tumor growth." (PMID 34295818, 2021). "Hence, decreased PARG activity can allow tumour cells to escape the PARPi mediated synthetic lethality." (PMID 33674744, 2021). "In human tumours, polβ-PARG co-expression adversely impacted survival in patients." (PMID 33674744, 2021). "Non-overlapping sensitivity to PARPi and PARGi may seem counter-intuitive, as PARP1/2 and PARG work in concert to repair DNA damage; one might expect that both PARPi and PARGi would be toxic towards tumour cells with defects in DNA damage repair." (PMID 34656146, 2021). "In addition, it is likely that PARG impinges on many other aspects of tumor biology, via regulation of oncogenic signaling pathways." (PMID 33005627, 2020). "Genetic manipulation of PARG suggests that PAR levels can impact tumor induction and progression." (PMID 33005627, 2020). "However, genetic manipulation of PARP and PARG suggests that PAR levels can also impact tumor induction and progression." (PMID 33005627, 2020). "Studies have shown that PARG also is associated with tumorigenesis, but the exact mechanism of PARG on tumor promotion has not been fully clarified." (PMID 31130856, 2019). "To determine whether PARG silencing affects BaP induced tumor formation in vivo, we implanted BaP induced tumor cells into Balb/c nude mice (n = 5 mice per group)." (PMID 27003318, 2016). "Finally, we aimed to investigate whether tumour expression of PARG could serve as a predictive biomarker for treatment with 5FU + irinotecan." (PMID 41451844, 2025).
tumor (continued). "Interestingly, SPON2, along with other differently expressed genes in 3 T3 overexpressing PARG, is also a tumor microenvironment regulator, which could indicates this mechanism to underlay the observed effect on 3 T3 derived tumor growth." (PMID 35585513, 2022). "Next, we tested whether PARG alone would facilitate tumor initiation from HMLE cells." (PMID 30459355, 2019). "Some tumour cells displayed slight sensitivity to PARG deficiency, but this sensitivity could not be correlated to BRCA1- or PTEN-deficiency." (PMID 27375368, 2016). "Both treatments reduced the growth rate (RTV) of HT29 PARG‐KO and NTC tumours with a more pronounced effect observed in the HT29 PARG‐KO tumours." (PMID 41451844, 2025). "We utilised a retrospective cohort of 170 primary FFPE tumour samples from metastatic CRC patients treated with first‐line irinotecan + 5FU and assessed PARG protein expression via IHC." (PMID 41451844, 2025). "This investigation established a PARG inhibitor (PDD00017273)‐resistant HCT116 cell line (HCT116RPDD) and evaluated its tumor biological characteristics." (PMID 36053937, 2023). "Corrected for the slight increase in tumor size due to DOX treatment alone (green graph), the true tumor-suppressing effect of PARG overexpression should actually be more dramatic than the apparent effect derived from comparison of two DOX-treated cell lines." (PMID 35585513, 2022). "In combination with a potent PARG inhibitor, the enhanced PARP1 activation triggers selective tumor cell apoptosis, with little effect on normal cells such as astrocytes." (PMID 34806016, 2021). "PARG, the PAR glycohydrolase that counterbalances PARP activity, is an emerging target with potential to selectively kill tumour cells harbouring oncogene-induced DNA replication and metabolic vulnerabilities." (PMID 34656146, 2021). "It would also be interesting to see if the induction of PARG expression in the tumors pre-formed in the absence of induced PARG would inhibit further tumor growth and even result in tumor volume reduction (shrinkage)." (PMID 35585513, 2022). "Many tumor cells express elevated levels of PARP1 and PARG, such as GSCs as we describe herein." (PMID 34806016, 2021). "Moreover, here, we determined PARG, a glycohydrolase involved in DNA-damage repair, and PARP-1 expression to better understand tumor cells going toward apoptosis after drug treatments." (PMID 34356835, 2021). "Because the non-metastatic cell line 67NR expresses PARG at nominal levels, we reasoned that PARG was not driving tumor growth in this model." (PMID 30459355, 2019). "We observed a 50% decrease in the number of MDA-MB-231 cells positive for ALDH activity when PARG was depleted, possibly explaining the lack of tumor initiation observed in vivo for PARG-depleted cells." (PMID 30459355, 2019). "Furthermore, our own results indicate that 78% of patients with PARG‐negative tumours had 3 or fewer liver metastases, whilst this percentage was lower (58%) in those with PARG expression (Fisher's test p = 0.01)." (PMID 41451844, 2025). "Notably, our findings showing a long‐term benefit in patients with PARG‐negative tumours were replicated in an independent cohort." (PMID 41451844, 2025). "In addition, PARG silencing decreased PARP1 and NF-kB expression which influenced DC and T cell fate to promote a more favorable CD4/CD8 ratio which could suppress tumor formation." (PMID 33005627, 2020). "In WT mice, the number of cells increased abnormally and tumorigenesis could be observed; however, no tumor tissue was found in PARG+/− mice." (PMID 31130856, 2019). "Thus, we hypothesized that the increased PARG expression seen in the more aggressive 67NR-derivative cells, such as 66cl4, may serve to promote tumor dissemination and metastasis, but likely not tumor outgrowth." (PMID 30459355, 2019).
tumor (continued). "HT29 PARG‐KO and NTC cells were used as negative and positive staining controls, respectively and helped us establish the positivity threshold in CRC primary tumour samples." (PMID 41451844, 2025).
infection (9 papers, 2013 to 2024). The state of being infected such as from the introduction of a foreign agent such as serum, vaccine, antigenic substance or organism. "ADP-ribosylation and the associated enzymes, including PARP and PARG, play an essential role in the ability of Trypanosomatidae to establish a successful infection in the human host." (PMID 37242378, 2023). "The association between pathogen and human PARPs/PARG is open to intervention that may create new treatments to reduce infection and its associated clinical manifestations." (PMID 37242378, 2023). "T. cruzi, in particular, is reliant on the proper function of its innate PARP and PARG enzymes to be able to maintain an infection within a human host." (PMID 37242378, 2023). "The PARG enzyme present in T. cruzi, denoted TcPARG, has been demonstrated as essential for epimastigote growth and the infection cycle in vitro." (PMID 37242378, 2023). "PARP and PARG enzymes remain credible targets for intervention in T. brucei as the parasite relies on both enzymes to establish infection." (PMID 37242378, 2023). "Infection with PVY or PVX themselves upregulated PARG expression, but to a lesser extent than dsRNA alone." (PMID 35887257, 2022). "The results obtained in PARG silenced cells showed that the presence of this enzyme is necessary in the host cell for the progression of the infection." (PMID 23776710, 2013). "Nevertheless, the poly(ADP-ribose) glycohydrolase activity from the host cell seems to be playing a fundamental role during the process of infection." (PMID 23776710, 2013). "Interestingly, HSV-1 E3 ligase protein ICP0 mediates the degradation of PARG specifically late in infection, although early inhibition by siRNA was inhibitory to infection." (PMID 38932138, 2024). "This work revealed that T. cruzi may rely on both innate and host PARG factors to allow successful infection in the human host." (PMID 37242378, 2023). "Notably, infection by herpesviruses was shown to induce PARylation by specifically downregulating PARG, in this way mimicking PARG inhibition." (PMID 34019811, 2021). "However, PARG enzymes could also be a target for inhibition themselves, given that TcPARG and hPARG are required for infection." (PMID 37242378, 2023). "Importantly, as with hPARP-1, T. cruzi seemingly uses host PARG during infection establishment." (PMID 37242378, 2023). "Inhibiting PARP can disrupt infection, but PARP inhibition leads to detrimental impacts for the host; therefore, being able to clear the accumulation of PAR with PARG enzymes would be required." (PMID 37242378, 2023). "A similar increase in polymerase activity for PARG overexpression was observed at a high multiplicity of infection (MOI = 1 and MOI = 5), but this was not significant (p<0.1), likely reflecting the incomplete efficiency of cDNA transfection." (PMID 31015836, 2019). "As a complementary analysis we evaluated the effect of TcPARG inhibition by pre-incubation of trypomastigotes in the presence of DEA for four hours previous to the initial infection, but the PARG inhibitor was not added to the cell culture medium afterwards." (PMID 23776710, 2013). "To ensure that the oncogenic effect observed in PARG-expressing cells was not due to disruption of another gene during cell infection, we depleted PARG in the HMLE-PARGwt cells using short hairpin RNA (shRNA) and observed a reduction of the capacity of the cells to invade matrigel." (PMID 30459355, 2019). "Furthermore, we found that PARG1 rather than PARG2 is the primary enzyme that confers poly(ADP-ribose) glycohydrolase activity in Arabidopsis during the tested responses to DNA damage and pathogen infection." (PMID 25950582, 2015).
brain disease (1 paper, 2020). "In addition, brain disease-induced ROS production triggers TRPM2 activation, leading to calcium influx from the extracellular space, and finally triggers cell death cascades that include PARP-1/PARG and caspase-dependent cell-death pathways." (PMID 32825703, 2020).
prostate (1 paper, 2022). "In addition, researchers looked at the involvement of poly(ADP-ribose) glycohydrolase (PARG), a PARP1-related regulatory protein, in prostate carcinogenesis." (PMID 35327610, 2022).
PARG also shares sentences with these, for which no sentence is quoted: lymphoma (2 papers); neurodegenerative disease (2); acute myeloid leukemia (1); adenocarcinoma (1); adrenocortical carcinoma (1); bacterial infections (1); brain injury (1); cervical squamous cell carcinoma (1); cholangiocarcinoma (1); diabetes (1); diffuse large B-cell lymphoma (1); disc degeneration (1); endocervical adenocarcinoma (1); esophageal cancer (1); esophageal squamous cell carcinoma (1); Intervertebral Disc Degeneration (1); invasive lobular carcinoma (1); ischaemia (1); kidney cancer (1); kidney chromophobe (1); malignant glioma (1); metastatic colorectal cancer (1); pancreatic ductal adenocarcinoma (1); promyelocytic leukemia (1); sarcoma (1); spinal cord injury (1); Stroke (1); testis cancers (1); thymic carcinoma (1); thymic epithelial tumors (1).